CYB561A3 (cytochrome b561 family member A3)
Description:
Transmembrane reductase that uses ascorbate as an electron donor in the cytoplasm and transfers electrons across membranes to reduce iron cations Fe(3+) into Fe(2+) in the lumen of the late endosome and lysosome. Reduced iron can then be extruded from the late endosome and lysosome to the cytoplasm by divalent metal-specific transporters. It is therefore most probably involved in endosomal and lysosomal cellular iron homeostasis.
Synonyms: LCytb; CYBASC3
Tractability: Antibody: UniProt predicts a signal peptide or a membrane-spanning region. PROTAC: its protein half-life has been measured.
Gene: Protein-coding gene on chromosome 11 (61,348,748 to 61,362,334, reverse strand). Ensembl gene ENSG00000162144.
Subcellular location: Late endosome membrane; Lysosome membrane
Subcellular location (Human Protein Atlas): Vesicles; Nucleoli
Gene Ontology:
Molecular function: protein binding; transmembrane ascorbate ferrireductase activity; oxidoreductase activity
Biological process: ascorbate homeostasis; intracellular iron ion homeostasis; transmembrane transport
Cellular component: lysosomal membrane; late endosome membrane; lysosome
Genetic constraint (gnomAD): Loss-of-function variants: 16 observed, 25.41 expected, observed/expected ratio (o/e) 0.63, 90% interval 0.43 to 0.96. The upper end of that interval is the gene's LOEUF score, 0.96, which puts it in group 4 of 6, group 1 being the genes least tolerant of losing a copy. Missense variants: 219 observed, 322.17 expected, observed/expected ratio (o/e) 0.68, 90% interval 0.61 to 0.76. Synonymous variants: 131 observed, 137.67 expected, observed/expected ratio (o/e) 0.95, 90% interval 0.82 to 1.1.
Homologues: Orthologues: chimpanzee CYB561A3 (100% identical), macaque CYB561A3 (97% identical), mouse Cyb561a3 (85% identical), rabbit CYB561A3 (82% identical), rat Cyb561a3 (82% identical), dog CYB561A3 (76% identical), guinea pig CYB561A3 (73% identical), pig CYB561A3 (69% identical), zebrafish cyb561a3a (55% identical), zebrafish cyb561a3b (49% identical), Drosophila melanogaster CG1275 (34% identical). Paralogues in human: CYBRD1 (43% identical), CYB561 (40% identical).
Diseases named in the same sentence as CYB561A3 in open-access papers:
CYB561A3 is named in the same sentence as 2 diseases in open-access papers, as found by Europe PMC text mining. Sharing a sentence is not in itself a finding about the gene and the disease. The quoted sentences say what the papers report.
Sepsis (1 paper, 2020). Sepsis is defined as life-threatening organ dysfunction caused by a dysregulated host response to infection. "The second most down-regulated gene is the cytochrome b561 family member A3 (CYB561A3) gene, which is normally expressed intercellularly as well as at the cell membrane and was found to be down-regulated in sepsis." (PMID 32151264, 2020).
vitiligo (1 paper, 2026). Generalized well circumscribed patches of leukoderma that are generally distributed over symmetric body locations and is due to autoimmune destruction of melanocytes. "We also identified candidate melanocyte markers, such as CYB561A3 and QPCT, with high melanocyte specificity and consistent downregulation in vitiligo." (PMID 41728299, 2026).